IGFBP2 (insulin like growth factor binding protein 2)
Diseases named in the same sentence as IGFBP2 in open-access papers (continued):
Sharing a sentence is not in itself a finding about the gene and the disease.
pancreatic cancer (25 papers, 2012 to 2024). "However, IGFBP2 showed a higher expression of genes associated with m6A fraction C in pancreatic cancer prognosis." (PMID 36831430, 2023). "IGFBP2 gene is a potential stroma-associated biomarker in pancreatic cancer." (PMID 33804861, 2021). "Furthermore, a high level of IGFBP-2 is associated with higher risk of peripancreas lymph node metastasis and it has been identified as an independent prognostic factor in pancreatic cancer." (PMID 28977895, 2017). "In conclusion, AAT, RAB2B, and IGFBP2 were identified as potential biomarkers of pancreatic cancer through plasma proteomic iTRAQ analysis and further validated using ELISA and immunohistochemistry." (PMID 36712921, 2023). "Analysis of these mechanisms has further established IGFBP2 as an important reference factor for the diagnosis and treatment of pancreatic cancer." (PMID 36712921, 2023). "Low serum level of IGFBP2 was considered as a predictive marker for the improvement of the overall survival of advanced pancreatic cancer patients." (PMID 32414222, 2020). "Knockdown of IGFBP-2 suppressed the proliferation, invasion and metastatic properties of pancreatic cancer cells, and it also increased the sensitivity to gemcitabine." (PMID 28977895, 2017). "In this study, we sought to determine the impact of IGFBP-2 expression on pancreatic cancer tumorigenesis and metastasis in vitro and in vivo." (PMID 28977895, 2017). "To determine the role of IGFBP-2 in pancreatic cancer cell migration and invasion, we compared its expression in five pancreatic cancer lines (Aspc-1, Bxpc-3, CFPAC, Panc-1 and SW1990) with that in HPDE." (PMID 28977895, 2017). "Our results provide novel insight of IGFBP-2 as a promising target to inhibit the metastasis and overcome the chemoresistance in pancreatic cancer." (PMID 28977895, 2017). "Our study showed that the sensitivity to gemcitabine was significantly enhanced after IGFBP-2 knockdown in pancreatic cancer cells." (PMID 28977895, 2017). "A better understanding of IGFBP-2 will ultimately improve our understanding of this “dark horse” in pancreatic cancer." (PMID 28977895, 2017). "All above results demonstrated that knockdown of IGFBP-2 inhibits migration and invasion of pancreatic cancer cells in vivo and in vitro." (PMID 28977895, 2017). "Taken together, these data indicated that knockdown of IGFBP-2 inhibits EMT in pancreatic cancer cells, at least in part, through the Hedgehog pathway by suppressing PTCH1." (PMID 28977895, 2017). "In established orthotopic pancreatic tumors, we found that knockdown of IGFBP-2 led to smaller tumor size, lighter tumor weight, and decreased the expression of Ki-67 in immunohistochemical analysis." (PMID 28977895, 2017). "The present study investigated the effects of IGFBP-2 on pancreatic cancer cell proliferation, migration and invasion and the chemosensitivity." (PMID 28977895, 2017). "Unfortunately, for these reasons, conclusions cannot be made about the LRRC19 > IGFBP2 classifier as a predictor for Src sensitivity in patients with advanced pancreas cancer in this trial." (PMID 23342270, 2012). "One possible explanation is that pancreatic cancer cells may secrete more IGFBP2 that cannot regulate the cancer-induced hyperglycemia." (PMID 39221034, 2024). "Characterization of IGFBP2-mediated pathways in pancreatic cancer cells may provide molecular insights into the progression of pancreatic cancer and suggest potential therapeutic targets for pancreatic cancer patients with elevated IGFBP2." (PMID 39221034, 2024). "IGFBP2 may be considered as a supplementary biomarker for the diagnosis and prognostic prediction in Chinese pancreatic cancer patients." (PMID 39221034, 2024).
pancreatic cancer (continued). "Furthermore, the diagnostic capability of combined AAT, RAB2B, IGFBP2, and CA19-9 for pancreatic cancer was significantly improved." (PMID 36712921, 2023). "On the basis of previous studies, it was thought that the IGF-1/IGFBP-2 ratio could differentiate patients with pancreatic cancer from the control group." (PMID 37373743, 2023). "AAT, RAB2B, and IGFBP2 could serve as effective biomarkers to facilitate the early diagnosis of pancreatic cancer." (PMID 36712921, 2023). "IGFBP2 has been identified as a potential biomarker of pancreatic cancer." (PMID 36712921, 2023). "However, IGFBP2 alone is insufficient for effective prediction of pancreatic cancer and needs to be combined with other indicators to improve accuracy and specificity of diagnosis." (PMID 36712921, 2023). "Furthermore, proteins that are encoded by the YAP-regulated genes EZR and IGFBP2 (ezrin and IGFBP2, respectively) promote metastasis and epithelial-to-mesenchymal transition (EMT) in pancreatic cancer cells." (PMID 29682330, 2018). "In addition to the inhibition of pancreatic cancer cell metastasis, IGFBP-2 also has an effect on cell proliferation." (PMID 28977895, 2017). "Additionally, inhibition of IGFBP-2 enhanced the sensitivity of pancreatic cancer cells to gemcitabine, suppressed tumor growth and potentiated the anti-tumor effect of gemcitabine in the orthotopic tumor model." (PMID 28977895, 2017). "Of these proteins, four proteins (apolipoprotein A-IV, apolipoprotein CIII, insulin-like growth factor binding protein 2 and tissue inhibitor of metalloproteinase 1) were significantly altered in pancreatic cancer in both the discovery and validation phase (P < 0.01)." (PMID 28514751, 2017). "In addition, IGFBP-2 promoted distant metastasis of pancreatic cancer cells in the orthotopic nude mouse model." (PMID 28977895, 2017). "IGFBP-2 inhibited pancreatic cancer cell proliferation in vitro." (PMID 28977895, 2017). "Interestingly, both IGFBP3 (two probes, more than eight folds) and IGFBP5 (three probes, more than 3 folds) are dramatically increased in both pancreatic tumor datasets, whereas, IGFBP2 is significantly decreased in both datasets." (PMID 26975989, 2016). "IGFBP2 has been found to be overexpressed in many malignant tissues, including pancreatic cancer." (PMID 24708694, 2014). "However, few studies have explored the relationship between IGFBP-2 and pancreatic cancer." (PMID 28977895, 2017). "Insulin-like growth factor binding protein 2 (IGFBP2) is overexpressed in tumor tissues of several malignancies, including pancreatic cancer." (PMID 39221034, 2024). "Insulin like growth factor binding protein 2 (IGFBP2) and IGFBP3 are also potential biomarkers for early-stage pancreatic cancer." (PMID 32447642, 2020). "On the other hand, BAG3‐positive PSCs also facilitate migration and invasion of nearby pancreatic cancer cells via secretion of soluble protein factors including IL‐8, MCP1, TGF‐β2 and IGFBP2." (PMID 31119886, 2019). "Insulin-like growth factor binding protein 2 (IGFBP-2) is a member of the IGFBP family of proteins, and it is highly expressed in pancreatic cancer patients’ serum and tumor tissues." (PMID 28977895, 2017). "Insulin-like growth factor binding protein 2 (IGFBP-2), one of six proteins in the IGFBP family, has been proposed as a potential biomarker in pancreatic cancer." (PMID 28977895, 2017). "Silencing IGFBP-2 inhibited invasion and metastatic properties, partially through inhibiting PTCH1 in pancreatic cancer." (PMID 28977895, 2017). "PTCH-1 is found contribute to the function of IGFBP-2 in suppressing metastasis and EMT of pancreatic cancer." (PMID 28977895, 2017). "One of the identified proteins, insulin-like growth factor binding protein-2 (IGFBP2), was further validated by western blotting to be elevated in pancreatic cancer juice and overexpressed in pancreatic cancer tissue." (PMID 24708694, 2014).
pancreatic cancer (continued). "Furthermore, collective application of AAT, RAB2B, IGFBP2, and CA19-9 in the diagnosis of pancreatic cancer was significantly more effective than each single index alone." (PMID 36712921, 2023). "Notably, IGFBP2 and IGFBP3 were identified as compensated biomarkers for carbohydrate antigen CA 19.9 in early-stage pancreatic cancer." (PMID 32414222, 2020). "Our results from wound healing and Transwell invasion assays indicated that knockdown of IGFBP-2 markedly inhibites pancreatic cancer cells migration and invasion compared with the negative control group." (PMID 28977895, 2017).
schizophrenia (21 papers, 2010 to 2025). A major psychotic disorder characterized by abnormalities in the perception or expression of reality. "Insulin‐like growth factor‐binding protein 2 (IGFBP‐2) was highlighted as another marker associated with lipid metabolism in patients with schizophrenia treated with AAs." (PMID 41017289, 2025). "Kl was identified as rare risk candidate for schizophrenia together with genes such as insulin-like growth factor binding protein 2 or ectonucleotide pyrophosphatase/phosphodiesterase 2, both upregulated in a rat model for schizophrenia." (PMID 23536833, 2013). "These genes included SBNO2, CEACAM5, AKAP1, UBC, ACTB, UBB, and FOS for schizophrenia; SEC24C, PGLYRP1, ARHGAP4, RPL22, SLC6A11, and SYK for bipolar disorder; and SRRT, PARK2, LILRA4, STK17A, IGFBP2, and NF1 for major depression." (PMID 22373040, 2011).
metabolic syndrome (20 papers, 2011 to 2025). A cluster of metabolic risk factors for CARDIOVASCULAR DISEASES and TYPE 2 DIABETES MELLITUS. "IGFBP2 is associated with multiple cardiovascular risk factors related to the metabolic syndrome and IR and is further regulated by LEP." (PMID 37329449, 2023). "Anyway, higher concentration of IGFBP2 at baseline was associated with a lower risk of incident metabolic syndrome, and vice versa." (PMID 33498859, 2021). "The notion that supports the implication of IGFBP2 with metabolic syndrome is that low IGFBP2 levels are associated with a deleterious lipid profile." (PMID 33498859, 2021). "Lower circulating levels of IGFBP-2 have been linked with an increased risk of developing metabolic syndrome and increased levels of triglyceride-rich particles." (PMID 32586279, 2020). "Indeed, studies reported that low IGFBP-2 independently associates with an increased risk of metabolic syndrome as well as elevated fasting glucose levels." (PMID 36970368, 2023). "The association of IGFBP2 with metabolic syndrome variables may explain in part its potential role in developing metabolic disease." (PMID 33498859, 2021). "IGFBP2, as a potential risk factor of insulin sensitivity, is related with metabolic syndrome." (PMID 33498859, 2021). "In men, low levels of IGFBP-2 have been reported to be associated with metabolic syndrome." (PMID 28846711, 2017). "In addition, in our study sample, median IGFBP-2 levels (233 ng/mL) were highly similar to the concentration of 220 ng/mL suggested as a cut-off value linked with the NCEP ATP III clinical criteria for the diagnosis of metabolic syndrome." (PMID 37854178, 2023). "While insulin-like growth factor 1 (IGF-1) exerts a cardioprotective effect in the setting of atherosclerosis, insulin-like growth factor binding protein 2 (IGFBP-2) is involved in metabolic syndrome." (PMID 36970368, 2023). "Our findings are in agreement with prior literature that reported IGFBP-2 to be a marker of metabolic syndrome and inversely correlate with BMI and triglyceride levels." (PMID 36970368, 2023). "IGFBP2 concentrations correlate with insulin sensitivity, and low levels of this protein are a marker for the metabolic syndrome." (PMID 23781310, 2012). "As already mentioned, the role of IGFBP2 on metabolic syndrome needs to be studied in depth." (PMID 33498859, 2021). "Indeed, several studies have reported that circulating IGFBP-2 was related to insulin sensitivity, metabolic syndrome and antidiabetic effect by regulate the expression of leptin gene." (PMID 31547433, 2019). "IGFBP-2 has been established as a marker of the metabolic syndrome and therefore, it has been suggested that low concentrations of IGFBP-2 could be a useful biomarker for the assessment of cardiovascular risk factors." (PMID 30061864, 2018). "In addition, serum IGFBP2 levels were significantly and independently associated with very LDL-triglycerides levels, which concludes in a metabolic alterations, being an early dyslipidemia but also for main cluster for metabolic syndrome." (PMID 33498859, 2021). "Moreover, we showed that regulation of the Sirt1-PPARα-IGFBP-2 signaling cascade by AMPK activator represents a novel pathway that could be applied to ameliorate metabolic syndromes by controlling IGF-1 homeostasis." (PMID 27009398, 2016). "IGFBP-2 has been found in fact to be possibly the most useful, among other peptides of the IGF system, in assessing nutritional status in preterm neonates during the early postnatal period, and in adults a strong association between low IGFBP-2 levels and metabolic syndrome has been identified." (PMID 22242132, 2011). "However, IGFBP2 is also a ligand for several targets capable of regulating inflammation associated signalling pathways in OA including PI3K/Akt/ MAPK/ PKC pathways whilst low IGFBP2 serum levels are associated with risk of metabolic syndromes and implicated in glucose and lipid metabolism." (PMID 38918843, 2024).
metabolic syndrome (continued). "This study also showed that low serum IGFBP2 was associated with elevated fasting glucose, triglycerides, and low-density lipoprotein (LDL)-cholesterol and positively correlated with insulin sensitivity, which could be a possible biomarker for metabolic syndrome." (PMID 33498859, 2021). "This highlights IGFBP-2 as a novel target for metformin action and AMPK-Sirt1-PPARα as a novel pathway to control metabolic syndrome." (PMID 32586279, 2020).
pancreatic ductal adenocarcinoma (19 papers, 2019 to 2025). An infiltrating adenocarcinoma that arises from the epithelial cells of the pancreas. "Plasma IGFBP2 levels were determined using enzyme-linked immunosorbent assay in 75 patients with pancreatic ductal adenocarcinoma (PDAC), 73 matched healthy controls, and 17 chronic pancreatitis patients." (PMID 39221034, 2024). "IGFBP2 has been reported to participate the macrophage based immunosuppressive microenvironment in pancreatic ductal adenocarcinoma." (PMID 37088808, 2023). "IGFBP2 significantly facilitated the invasion and metastasis of pancreatic ductal adenocarcinoma via the NF-κB signaling pathway." (PMID 37006311, 2023). "Recently, it has been shown that IGFBP2 induces selective polarization of pancreatic ductal adenocarcinoma macrophages via the STAT3 pathway, which leads to the macrophage-based immunosuppressive microenvironment in PDAC and thus promotes tumor progression." (PMID 35989938, 2022). "A recent study of pancreatic ductal adenocarcinoma patients links mammalian IGFBP2 to cachexia, suggesting that the insulin/IGF signaling-related mechanism of cancer cachexia is conserved." (PMID 35319749, 2022). "Consistent with this, in the adult fly cachexia models, ImpL2 leads to adipose tissue wasting, reminiscent of the recent finding that IGFBP2 is a biomarker for cancer cachexia in human pancreatic ductal adenocarcinoma patients." (PMID 35319749, 2022). "IGFBP2 promotes tumor progression in pancreatic ductal adenocarcinoma through the STAT3 pathway." (PMID 35203526, 2022). "Again, different conclusions about the role of IGFBP-2 have been drawn in other types of cancers such as pancreatic ductal adenocarcinoma (PDAC), where IGFBP-2 promoted EMT: downregulation of N-cadherin and upregulation of E-cadherin followed knockdown of IGFBP-2." (PMID 31903164, 2019). "Two independent studies demonstrate that IGFBP-2 correlates with worsened survival in pancreatic ductal adenocarcinoma (PDAC) and that IGFBP-2 stimulates STAT3 signaling, leading to immune suppression phenotypes." (PMID 41226289, 2025). "In both pancreatic ductal adenocarcinoma (PDAC) and hepatocellular carcinoma (HCC), IGFBP2 induces epithelial-mesenchymal transition (EMT) by activating the NF-κB signaling pathway." (PMID 40821817, 2025).
pulmonary fibrosis (17 papers, 2016 to 2026). Chronic progressive interstitial lung disorder characterized by the replacement of the lung tissue by connective tissue, leading to progressive dyspnea, respiratory failure, or right heart failure. "Our previous study demonstrated that loss of IGFBP2 function specifically in AEC2 cells promotes lung fibrosis." (PMID 40121473, 2025). "In previous studies, we identified that IGFBP-2 was positively associated with lung fibrosis in serum and induced sputum of IPF patients." (PMID 34035374, 2021). "Similarly, IGFBP2 has been implicated in mitigating senescence in pulmonary fibrosis models." (PMID 41170754, 2026). "IGFBP-1 and IGFBP-2 have previously been shown to predict mortality in heart failure and are elevated in other fibrotic diseases, such as idiopathic pulmonary fibrosis." (PMID 41226753, 2025). "Conversely, intranasal delivery of recombinant IGFBP2 or overexpression of IGFBP2 reduced lung cell senescence and thereby alleviate lung fibrosis." (PMID 38566093, 2024). "Serum IGFBP1 and IGFBP2 are elevated in idiopathic pulmonary fibrosis patients and IGFBP2 level was significantly reduced by anti-fibrotic therapy." (PMID 30214426, 2018). "We conclude that serum IGFBP-1 and IGFBP-2 are increased in patients with idiopathic pulmonary fibrosis in comparison to healthy subjects." (PMID 27215343, 2016). "Serum IGFBP-1 and −2 are increased in idiopathic pulmonary fibrosis and IGFBP-2 may be reduced by anti-fibrosing therapy." (PMID 27215343, 2016). "A previous study by our group demonstrated that downregulation of IGFBP2 mediates senescence specifically in AEC2 cells through the P21 signaling pathway, contributing to the development of pulmonary fibrosis." (PMID 40121473, 2025). "Overall, these results indicate that IGFBP2 transcript levels were low in AEC2 cells of both severe and moderate-COVID mediated lung fibrosis." (PMID 40121473, 2025). "Namely, similar to pulmonary fibrosis, the expression of PPARA and IGFBP2 significantly decreased, and that of the senescence marker p21 (CDKN1A) increased in the A549 cells exposed to DEP." (PMID 39103936, 2024). "Although IGFBP-2 has been suggested to have a role in idiopathic pulmonary fibrosis, its role in hepatic fibrosis is not clear." (PMID 38541155, 2024). "Other studies on lung fibrosis identified a significant increase of IGFBP-2 in BAL fluid and in lung tissue of ILDs without focusing on SSc39." (PMID 34035374, 2021). "Findings with IGFBP2 are consistent with our previous studies showing increased expression of IGFBP3 and IGFBP5 in IPF and SSc-PF and reinforced the crucial role that IGFBPs and the IGF pathway play in the development and perpetuation of pulmonary fibrosis." (PMID 32210969, 2020). "The assay of IGFBP-2 in the serum of patients with idiopathic pulmonary fibrosis had never been done before." (PMID 27215343, 2016).